G6PD (glucose-6-phosphate dehydrogenase)
Diseases named in the same sentence as G6PD in open-access papers (continued):
Sharing a sentence is not in itself a finding about the gene and the disease.
tumor (continued). "Recent evidence suggested that OGT promotes O-GlcNAcylation of G6PD, and this process is critical for G6PD activation and tumor progression." (PMID 34354953, 2021). "Previous investigations demonstrated that the expression of G6PD in tumor cells contributed to resistance to various chemotherapeutic agents, including oxaliplatin." (PMID 33718248, 2021). "Pol ι was shown to stimulate Erk signaling to enhance OGT expression, and the G6PD inhibitor polydatin attenuated Pol ι induced tumor growth in vitro and in vivo." (PMID 34354953, 2021). "This study is the first to identify correlation between 6-phosphate dehydrogenase and the abundance of tumor macrophages, which will provide a new direction for further exploration of the mechanism of G6PD in regulating HCC development." (PMID 33413205, 2021). "The results showed that HK2, PGM1, PPP1R3C, GYS1, and G6PD were significantly up-regulated in ccRCC tumor tissues." (PMID 34522206, 2021). "As this approach has been successfully used to identify the activity of G6PD and other enzymes in tumor tissue, we adapted it for application on epidermis." (PMID 32713735, 2020). "PGK1 and G6PD were found closely correlated with the metastatic potential of tumor cells, and CTCs from prostate cancer patients presented heterogeneous expression of these genes." (PMID 32028979, 2020). "We found that G6PD is not only a useful prognostic marker, but also acts as an indicator to classify cases based on the tumor immune activity and a potential biomarker for immune checkpoint blockade therapy." (PMID 33361404, 2020). "High G6PD expression was found to be a poor prognostic factor in BCa, and the level of G6PD expression increased as the tumor stage progressed." (PMID 32189139, 2020). "G6PD and pSTAT3 was mainly localized in the cytoplasm and nucleus of the ccRCC tumor cells, respectively; whereas the predominant localizations of p65 was seen within the whole ccRCC cells." (PMID 33041664, 2020). "That is why the oppression of G6PD is one of the potential strategies for tumor growth inhibition and overcoming drug resistance." (PMID 32842595, 2020). "Through a multi-factor weighted model enrolling the array results, cell validation, expression rates in CTCs and metastasis-related functions reported by literature, PGK1 and G6PD were determined the optimal metabolic markers related to tumor metastasis." (PMID 32028979, 2020). "Our recent study has revealed a novel tumor suppressive role for the glycolytic enzyme Aldob in HCC through directly binding to G6PD and inhibiting its activity, acting as a metabolic switch in glucose metabolism and regulating the metabolic reprogramming." (PMID 33275593, 2020). "Increased expression of PGK1 and G6PD, as critical regulators involved in glycolysis and the pentose phosphate pathway, respectively, reveals active glucose metabolism of tumor cells." (PMID 32028979, 2020). "The results demonstrated that 16 of 27 (59.3%) tumor species exhibited high G6PD expression levels, and the statistical analysis revealed that the mRNA expression level of G6PD was significantly increased in ccRCC species compared with normal tissues." (PMID 33041664, 2020). "Together, our results highlight an underlying role of tumor metabolism in PDAC drug response and identify G6PD as a target to overcome drug resistance." (PMID 32974013, 2020). "Our strategy is that, by accumulating FDG-bound G6PD preferentially in tumor cells, uncompetitive inhibition of G6PD by fluasterone will be driven to reach irreversibility preferentially in tumor cells." (PMID 35582271, 2019). "G6PD is up-regulated in many tumor cells and tumor tissues and generally its level correlates with the overall survival of patients." (PMID 31850189, 2019).
tumor (continued). "For instance, drug targeting or knocking down glucose transporter, hexokinase, pyruvate kinase M2, lactate dehydrogenase A and glucose-6-phosphate dehydrogenase (G6PD) can affect the metabolism in tumor cells and drug resistance of tumors." (PMID 33817181, 2019). "The knockdown of G6PD expression with siRNA decreased tumor cell proliferation and enhanced apoptosis." (PMID 31027492, 2019). "Their juncture at uncompetitive inhibition of G6PD constitutes substantial evidence for the stepwise evolution of the anthropoid primate-specific kill switch tumor suppression system, culminating in humans (Supplementary Section 2)." (PMID 30400061, 2019). "For example, by combining 1,25(OH)2D3 with G6PD-inhibiting regimens, substantial anti-tumor effects were observed." (PMID 30181873, 2018). "We found that in HCC samples the transcript levels of the rate limiting enzyme glucose-6-phosphate dehydrogenase (G6PD) were significantly higher than those in adjacent non-tumor (P < 0.0001) and normal livers (P < 0.0001) samples, respectively." (PMID 30430110, 2018). "We found that the upregulation of G6PD correlates with higher tumor grade, increased tumor recurrence, and poor patient survival." (PMID 29904144, 2018). "Multi-comparison analysis revealed a significant difference in G6PD expression among progressing tumor grades." (PMID 29904144, 2018). "In the present study, we further explore the association between G6PD and RCC through data mining of the public Gene Expression Omnibus (GEO) of 72 ccRCC and the adjacent non-tumor tissues (GSE53757)." (PMID 29312589, 2017). "Ectopic Glucose 6-phosphate dehydrogenase (G6PD) expression plays important role in tumor cell metabolic reprogramming and results in poor prognosis of multiple malignancies." (PMID 29312589, 2017). "Doxycycline (Dox) treatment administered in the drinking water, which suppressed Plk1 expression, dramatically abolished WT G6PD-promoted tumor growth." (PMID 29138396, 2017). "Western blotting using the tumor tissue lysates confirmed the overexpression of Plk1 and the knockdown of G6PD by shRNAs in Hep3B xenografts." (PMID 29138396, 2017). "In particular, G6PD arises as an interesting candidate for therapeutic intervention, as it regulates key metabolic processes in tumor cells, such as synthesis of ribose, fatty acids and redox homeostasis." (PMID 29290982, 2017). "Surprisingly, depleting proteins like G6PD or JNK had little effect on tumour explant growth, though they both strongly induced cell death in our wing disc model." (PMID 28912546, 2017). "TKT and G6PD have been postulated as relevant enzymes in tumor cells by different studies, but little is known about the impact of the expression level of these enzymes on disease progression and survival." (PMID 29290982, 2017). "Taken together, these results demonstrate that G6PD and its phosphorylation-related activation are critical for Plk1-mediated tumor growth in vitro and in vivo." (PMID 29138396, 2017). "Taken together, G6PD promotes tumor cell proliferation possibly through ROS-stimulated persistent activation of p-STAT3 signaling and up-regulated CyclinD1 expression in RCC." (PMID 29312589, 2017). "Western blotting using the tumor tissue lysates confirmed the knockdown of Plk1 and the overexpression of G6PD WT and mutants in HeLa xenografts." (PMID 29138396, 2017). "We found that the growth of tumor and tumor size were significantly faster and larger with G6PD-overexpressing cells compared with the control cells." (PMID 29312589, 2017). "The G6PD-knockdown group treated with oxaliplatin proved a large reduction in tumor weight and tumor growth." (PMID 28692052, 2017).
tumor (continued). "Numerous studies have revealed a significant upregulation of G6PD in tumor cells and neoplastic tissues." (PMID 28553614, 2017). "Over the years vast quantities of results dealing with the relevance of the two molecules—G6PD and Par-4—in tumor growth were published." (PMID 27872579, 2016). "Hexokinase activity and hexose concentration (175%) was found to be increased, whereas glucose-6-phosphatase (33%), fructose-1, 6-bisphosphatase (42%), and G6PD (5 fold) activities were reduced in tumor mass compared to control." (PMID 28096627, 2016). "The enzyme G6PD generates the reductive metabolite NADPH, which has antioxidant effects, but has also been linked to tumour growth." (PMID 26976705, 2016). "The activity of glucose-6- phosphate dehydrogenase was found to be significantly reduced (p<0.001) in tumor mass compared to the normal healthy tissue." (PMID 28096627, 2016). "After discovering of prostate apoptosis response-4 (Par-4) by the end of 1990 data regarding this molecule were recorded and analyzed, too, and interpreted in the context of knowledge about the role of G6PD in normal cells as well as in tumor ones." (PMID 27872579, 2016). "On the other side inhibition of G6PD breaks the energy supply of tumor cells, weakens their defence against oxidative stress and thereby enhances the sensitivity of tumor cells to oxidative agents (e.g. chemotherapy)." (PMID 27872579, 2016). "Tumor sizes were smaller in the miR-1 overexpression groups (plenti-miR-1 and plenti-miR-1 + G6PD control) than in the other groups between 16 and 27 days post-injection (P < 0.05)." (PMID 27861141, 2016). "Collectively, the current study established a tumor suppressor-like function of BAG3 via direct interaction with G6PD in HCCs at the cellular level." (PMID 26621836, 2016). "In another pre-clinical study, treatment with adrenocortical steroid dehydroepiandrosterone (DHEA), a powerful inhibitor of G6PD, inhibited tumor development." (PMID 27861141, 2016). "Western blotting analysis confirmed that Flag-tagged WT or S84V G6PD proteins were retained in tumours and that WT G6PD was O-GlcNAcylated in vivo." (PMID 26399441, 2015). "We found that the G6PD mRNA level in the tumor (10/13=76.9%) and non-tumor tissues (7/13=53.8%) dramatically increased compared with the normal group." (PMID 26583321, 2015). "Mice injected with S84V G6PD replacement cells showed a significant delay in tumor formation compared with mice injected with WT G6PD replacement cells, producing tumours with much smaller total mass." (PMID 26399441, 2015). "The model elucidates an important role for NAPDH supply, as modulated by G6PD activity, in controlling concentration-dependent doxorubicin cytotoxicity in tumor cells." (PMID 21935349, 2011). "The sequence heterogeneity of the HPRT and G6PD genes was also determined on DNA from tumor tissues." (PMID 20186333, 2010). "Passaged tumours retain human lactate dehydrogenase and glucose-6-phosphate dehydrogenase isoenzyme patterns and a human chromosome constitution." (PMID 629858, 1978). "Additionally, the growth and survival of KRAS-driven tumor cells are supported by G6PD through the maintenance of NADPH levels and antioxidant capacity." (PMID 41328353, 2026). "Notably, TTC1 and G6PD exhibited significantly higher expression levels in tumor cells comparedto other cell types within the TME." (PMID 41268553, 2025). "G6PD enhances NADPH production, which is associated with poor tumor prognosis." (PMID 41469472, 2025). "And after G6PD knockdown, the tumor volume and weight in vivo were significantly reduced." (PMID 40621461, 2025). "Therefore, high G6PD expression not only promotes tumor proliferation and growth but also regulates ROS levels to enhance tumor cell survival." (PMID 40978482, 2025).
tumor (continued). "The accumulated evidence strongly suggests that BANCR may exert its tumor-suppressive effect on ccRCC through interaction with G6PD." (PMID 39894218, 2025). "Moreover, G6PD has been shown to facilitate tumor migration and invasion through the induction of epithelial-mesenchymal transition, thereby promoting metastasis." (PMID 41268553, 2025). "Additionally, enzymes like fatty acid synthase (FASN) and glucose-6-phosphate dehydrogenase (G6PD) support lipid biosynthesis and antioxidant defence, respectively, to fulfil the biochemical demands of rapidly proliferating tumours." (PMID 41154605, 2025). "In addition, we evaluated the expression level and activity of G6PD in mouse tumor tissues as well as the content of R-5P." (PMID 39894218, 2025). "We also validated TTC1, PANK2 and G6PD expression levels in tumor by RT-qPCR." (PMID 41268553, 2025). "Furthermore, it has been reported that MDM2 can promote tumor metabolic reprogramming by enhancing glucose uptake or directly activating pathways such as G6PD." (PMID 41203626, 2025). "Previous studies have shown that G6PD plays an important role in tumor occurrence and development." (PMID 40166471, 2025). "In addition to SIRT2, HDAC10 can also reduce G6PD transcription by inhibiting the expression of the histone acetylation, decreasing lung cancer cell proliferation and tumour growth." (PMID 39778006, 2025). "Additionally, G6PD overexpression, which leads to lactate accumulation and the formation of an acidic microenvironment, has been shown to increase tumor cell tolerance to chemotherapy." (PMID 40685383, 2025). "On the other hand, G6PD silencing might contribute as well to tumor aggressiveness, albeit through a different mechanism." (PMID 38115544, 2024). "More importantly, the NADP+ was decreased in tumors compared with non-tumor liver tissue in this tumor model, likely caused by the elevated G6PD." (PMID 39353892, 2024). "In this context, one of the key functions of G6PD in tumor growth may be protection from cell death." (PMID 39796677, 2024). "Researches showed that expression of G6PD in tumor cells is higher than that in normal cells." (PMID 39080260, 2024). "Moreover, RT-qPCR results further showed a positive correlation between the expression levels of Fra-1 and key molecules of the oxidative branch of the PPP pathway (G6PD, 6PGD) in mouse transplanted tumor tissues." (PMID 39624082, 2024). "In vivo, 6-An mediated inhibition of G6PD enzyme activity, inhibiting tumor proliferation." (PMID 38291438, 2024). "Further investigation is needed to understand how this composition change is associated with the slow tumor growth observed in the absence of G6PD." (PMID 38997257, 2024). "G6PD altered aerobic glycolysis and promoted tumor progression via pentose phosphate pathway." (PMID 38184549, 2024). "WB experiment showed that the levels of G6PD increased in tumor tissues than in lung tissue." (PMID 38194707, 2024). "While accurately discerning differences in gene expression between liver normal and tumor tissues might be challenging, preliminary findings revealed elevated expressions of G6PD, STMN1, and PML in HCC tissues in comparison to normal liver tissues." (PMID 38317842, 2024). "Our in vivo isotope tracing and flux analysis revealed that G6PD deficiency in KL lung tumors does not affect glucose carbon flux to tumor pyruvate, lactate, and TCA cycle intermediates." (PMID 38997257, 2024). "Furthermore, IGF2BP2 was identified as crucial for stabilizing G6PD, promoting tumor growth and metastasis." (PMID 39138186, 2024).
tumor (continued). "Additionally, upon treating tumor cells with siIGF2BP2, we observed a decrease in G6PD protein levels." (PMID 39138186, 2024). "Even though the expression of G6PD was significantly high in primary tumours compared to normal kidney tissues, and a similar trend was noted in normal tissues versus different stages of ccRCC, it was not a good prognostic indicator in the context of OS in ccRCC patients." (PMID 37174052, 2023). "Moreover, since NADPH is also pivotal for redox homeostasis, G6PD also plays a significant role in tumor cell survival and drug resistance." (PMID 38139067, 2023). "However, a pattern of an increased expression of G6PD was noted in matching primary compared to metastatic tumours." (PMID 37174052, 2023). "Indeed, previous studies have reported that the combination of G6PD inhibitors with anti-tumor drugs, such as doxorubicin, 5-FU, and paclitaxel, can be a promising strategy in treating tumor and reversing chemotherapeutic resistance." (PMID 38139067, 2023). "In other words, high expression of G6PD is indeed involved in anti-tumor drug resistance." (PMID 37601657, 2023). "The detailed biological function of G6PD in tumor cells still needs to be studied." (PMID 37601657, 2023). "And the expression level of G6PD is related to the overall survival of tumor patients." (PMID 37601657, 2023). "Furthermore, G6PD is not only essential for maintaining redox homeostasis but it also plays a significant role in tumor cell metabolism." (PMID 38139067, 2023). "Moreover, apart from involvement in metabolism, cell proliferation and apoptosis, and tumor immunity, the high expression of G6PD plays a pivotal role in chemotherapy resistance." (PMID 37601657, 2023). "Furthermore, we demonstrated that RMRP contributes to BLCA tumor progression via a novel ceRNA network: the miR-206/G6PD axis." (PMID 37958478, 2023). "Furthermore, the intricate mechanisms that regulate G6PD, as well as the metabolic pathways influenced by G6PD, form a complex network that contributes to the survival and proliferation of tumor cells." (PMID 38139067, 2023). "Thus, G6PD inhibition was shown to be beneficial in reversing chemotherapy resistance in tumor cells." (PMID 37190196, 2023). "In vivo, G6PD impairment significantly inhibits KEAP1 mutant tumor growth." (PMID 36843949, 2023). "Knocking down PBX3 significantly slowed down the growth of the xenografted tumors formed by HCT116p53null cells, whereas G6PD overexpression prevented this suppressive effect, thus restoring the tumor growth rate as well as the size and weight of the generated tumors." (PMID 37781025, 2023). "Upregulation of G6PD is present in various tumors, and increased G6PD expression leads to increased biosynthesis of nucleotides and lipids necessary for cell division and proliferation, favoring tumor cell proliferation." (PMID 40625719, 2023). "Additional studies have shown that G6PD promotes tumor growth by protecting cells from ROS." (PMID 36843949, 2023). "Meanwhile, aspirin—which is known as an antipyretic and analgesic drug—could exert anti-tumor functions by increasing G6PD acetylation-mediated oxidative stress, thereby reducing tumor cell proliferation." (PMID 38139067, 2023). "G6PD plays a role in cell cycle regulation (cell growth and death) and is related to tumorigenesis and malignant progression; in addition, it is an indicator of poor tumor prognosis." (PMID 36816364, 2023). "Indeed, while challenges—including side effects—still remain, small-molecule G6PD inhibitors showing potential anti-tumor effect either when used alone or in combination with other anti-tumor drugs have been developed." (PMID 38139067, 2023). "Furthermore, G6PD knockdown with Escin treatment achieved a more pronounced inhibition of tumor volume." (PMID 37149513, 2023).